MFN2 (mitofusin 2)
Diseases named in the same sentence as MFN2 in open-access papers (continued):
Sharing a sentence is not in itself a finding about the gene and the disease.
neurodegenerative disease (31 papers, 2010 to 2025). A disorder of the central nervous system characterized by gradual and progressive loss of neural tissue and neurologic function. "Previous studies reported that mutations in human Mfn2 or OPA1 were related to neurodegenerative diseases." (PMID 41299984, 2025). "This work reveals that metformin delays astrocyte senescence via inhibiting astrocytic Mfn2-cGAS activation and suggest that metformin is a promising therapeutic agent for age-associated neurodegenerative diseases." (PMID 38566081, 2024). "Heterogeneous mutations in the mitochondrial fusion gene mitofusin 2 (MFN2) cause the neurodegenerative disease Charcot-Marie-Tooth type 2A (CMT2A)." (PMID 37108237, 2023). "In this context, proteins that directly modulate mitochondrial fusion have been found mutated in neurodegenerative diseases like Charcot-Marie-Tooth 2A (Mitofusin-2 (Mfn2);) or autosomal-dominant optic nerve atrophy (optic atrophy protein 1 (OPA1);)." (PMID 20064504, 2010). "Although it has been controversial whether loss of MFN2 induces or relieves the symptoms of neurodegenerative diseases, it is plausible that MFN2 activity needs to be fine-tuned to maintain proper neurobiological homeostasis." (PMID 37550059, 2023). "Numerous studies have highlighted the prominent roles of MFN2 in maintaining mitochondria homeostasis and function, while the disruption of MFN2 has been shown to lead to mitochondrial breakdown and is implicated in various disorders, including neurodegenerative diseases." (PMID 36232745, 2022). "Mutations in MFN2 cause the neurodegenerative disease Charcot-Marie-Tooth type 2A (CMT2A)." (PMID 31664033, 2019). "Although Mfn1 and Mfn2 have similar functions and are even functionally complementary in specific situations, only mutations in Mfn2 cause significant physiological changes leading to neurodegenerative diseases, such as type 2A peroneal muscular atrophy neuropathy." (PMID 34604240, 2021). "Defects in MFN2- and MFN1- mediated mitochondrial fusion have been associated with various neurodegenerative diseases, including PD." (PMID 41035822, 2025). "This included two known proteins associated with MERCS, MFN2 and TOMM40, as well as neurodegenerative disease-associated genes such as WIPI2, CLASRP, BAG6, SOD1 and FUS which increase MERCS and MTCH2 and PARL which decrease MERCS." (PMID 38467609, 2024). "In the group of dynamics and homeostasis, three VUS were identified; one of them was novel in the MFN2 gene and present in two siblings (P73 and P74) with a similar clinical picture of neurodegenerative disease." (PMID 38465286, 2024). "Because MFN2 plays a crucial role in controlling mitochondrial structure, MFN2 is related to neurodegenerative diseases." (PMID 37107583, 2023). "It is thus likely that MFN2 has a protective effect on synapses in a wide range of muscular and neurodegenerative diseases." (PMID 34114603, 2021). "Indeed, dysfunction in the major components of the fission and fusion machineries of the mitochondria, including dynamin-related protein 1 and mitofusin 1 and 2 (MFN1 and MFN2), was found to result in neurodegenerative diseases." (PMID 36835316, 2023). "In particular, overexpression of the mutant form of MFN2 in adult mice induces progressive neurodegeneration and significant abnormalities in behavior, learning, and memory, which are similar to those seen in human neurodegenerative diseases." (PMID 37550059, 2023). "Previous studies have shown that Mfn2 agonists could reverse mitochondrial defects in preclinical models of neurodegenerative disease of Charcot Marie Tooth disease type 2A (CMT2A) by mechanistically ameliorating mitochondrial trafficking." (PMID 33627689, 2021). "Yet, complete absence of either MFN1 or MFN2 is embryonic lethal in mice and mutationsin MFN2 are associated with metabolic and neurodegenerative diseases in humans." (PMID 34178146, 2018).
neurodegenerative disease (continued). "The administration of AAV9-KD-rMFN2 resulted in the satisfactory silencing of endogenous MFN2 and overexpression of exogenous MFN2 in the CNS of MitoCharc1 mice, in accordance with the data obtained by AAV9 gene therapy for other neurodegenerative diseases." (PMID 38007410, 2023). "Evidence indicates potential correlations between the MFN2/UCP4 genes and AD, a progressive neurodegenerative disease." (PMID 36877954, 2023). "The proteins involved in neurodegenerative diseases such as DRP1 (dynamin related protein 1) and MFN2 (mitofusin 2) are enriched in MAMs and the perturbation of mitochondria-ER contacts has been described in neurodegenerative disorders, including PD, AD and ALS." (PMID 30231533, 2018).
infection (26 papers, 2008 to 2024). The state of being infected such as from the introduction of a foreign agent such as serum, vaccine, antigenic substance or organism. "Myeloid-specific MFN2 deficiency impairs immune responses during infection with Listeria and M. tuberculosis and during lipopolysaccharide (LPS)-induced septic shock." (PMID 34482801, 2021). "It was also reported in another study that MFN2 expression was reduced after infection of the H37Rv strain (pathogenic M. tuberculosis laboratory strain) in human monocytic THP-1 cells, which correlated with the structural alteration observed in the mitochondrial population." (PMID 36076909, 2022). "MFN2-mediated crosstalk between mitochondrial dynamics and innate immune responses may determine the outcomes of pathogenic infections." (PMID 34482801, 2021). "In addition, MFN2 deficiency led to a significant decrease in the level of co-localization between Mtb phagosomes and lysosomes after infection." (PMID 33972668, 2021). "To understand how EV-D68 induces mitochondrial fragmentation and mitophagy, we examined the expression levels of proteins that regulate mitochondrial dynamics, including MFN-2 and Drp-1, upon EV-D68 infection." (PMID 39677747, 2024). "Initial Western blot studies indicated that multiplicity of infection (MOI) = 5 significantly increased Mfn2 protein in PAECs." (PMID 38139362, 2023). "Another study described that infection with mycobacterium tuberculosis up-regulated the expression of MFN2 and promoted the assembly and activation of the NLRP3 inflammasome." (PMID 35250595, 2022). "Although infection with Sp induced a significant decrease in the protein levels of MFN2 in 16HBE cells compared to the medium control, Sp infection with CSE pre-exposure did not affect the MFN2 protein." (PMID 35681466, 2022). "And the Elisa assay results also showed that the IFN-λ3 content in the supernatant in Ad-Mfn2 group was also decreased (P < 0.01) compared to WT group after SVV infection." (PMID 35958608, 2022). "Taken together, these data strongly suggest that MFN2-mediated induction of HIF-1α is essential for the activation of inflammatory signaling in macrophages during infection." (PMID 33972668, 2021). "Collectively, these data suggest that MFN2 is required for mitochondrial respiratory complex I and mtROS production in macrophages during infection." (PMID 33972668, 2021). "We generated two MFN2-knockdown hESC lines (MFN2 RNAi #1 and #2) using lentivirus infection that expressed shRNA targeting MFN2." (PMID 34602978, 2021). "In this article, we summarize the current knowledge on the role of MFN2 in the crosstalk between mitochondrial dynamics, innate immunity, and immunometabolism in macrophages during infection." (PMID 34482801, 2021). "We therefore evaluated the association of MFN2 with late-endosomal protein Rab7 and lysosomal protein LAMP1 in macrophages in the context of infection." (PMID 33972668, 2021). "In accordance with these findings, our recent data suggest that myeloid MFN2 is required for inflammatory and antimicrobial responses during infection with Listeria or M. tuberculosis." (PMID 34482801, 2021). "Upon infection with RNA viruses such as influenza virus, NLRP3 and MAVS associate with MFN2 in a mitochondrial membrane potential (ΔΨm)‐dependent manner." (PMID 34337844, 2021). "In this article, we highlight the fine-tuning role of MFN2 in host responses against various infections and inflammatory stimuli." (PMID 34482801, 2021). "Future studies are needed to clarify the exact underlying molecular and biochemical mechanisms through which MFN2-Rab7 crosstalk contributes to innate host defense during infection." (PMID 33972668, 2021). "Together, these results indicate that MFN2 is involved in the prevention of excessive mitochondrial fragmentation during infection." (PMID 33972668, 2021). "Mechanistically, MFN2 binds NLRP3 to promote IL-1β secretion after infection with influenza virus and EMCV." (PMID 34482801, 2021).
infection (continued). "We examined apoptosis after infection with Rv or Ra in MFN2-silenced macrophages using Annexin V/PI staining." (PMID 31671648, 2019). "After infection with the MFN2-overexpressing adenovirus, the expression of the MFN2 protein was significantly increased." (PMID 31024347, 2019). "Our data shows that MFN-2 is cleaved late during EV-D68 infection by the viral 3C protease, suggesting that mitofusin-2 may be detrimental to EV-D68 release." (PMID 39677747, 2024). "However, unlike mitophagy induced by MFN-2 depletion, which causes complete mitophagy as evidenced by the reduction in TOMM20 staining in MFN-2-depleted cells, EV-D68 infection induces incomplete mitophagy and uses the mitophagosomes for nonlytic viral egress." (PMID 39677747, 2024). "Therefore, our studies were carried out to investigate the possible mechanisms of how Mfn2 affects immune response in PK-15 cells infection with SVV and find out the relationship between Mfn2, inflammasome and RIG-I signaling pathway." (PMID 35958608, 2022). "Mfn2 expression was measured using qRT-PCR and western blot after 5 days of infection." (PMID 35337368, 2022). "The MFN2-induced aerobic glycolysis during infection is at least partly mediated by HIF-1α." (PMID 34482801, 2021). "During infection with Mtb, M. bovis BCG (BCG), and M. abscessus, macrophages from Mfn2 CKO mice had a higher capacity to replicate, with higher levels of intracellular colony forming units (CFUs) at different multiplicities of infection (MOIs), as compared to BMDMs from Mfn2 WT mice." (PMID 33972668, 2021). "Elucidation of the MFN2-mediated signaling networks will not only provide important insights into metabolic rewiring in innate immune cells but also uncover therapeutic targets to treat infections." (PMID 34482801, 2021). "In addition, iNOS (Nos2) mRNA expression was significantly lower in PMs from Mfn2 CKO mice than in Mfn2 WT PMs during infection with LM." (PMID 33972668, 2021). "We next assessed whether MFN2 expression affected the host defense against LM intravenous (i.v.)or intraperitoneal (i.p.)infection." (PMID 33972668, 2021). "In addition, the number of granulomatous lung lesions was significantly increased in Mfn2 CKO mice compared to Mfn2 WT mice after infection with BCG." (PMID 33972668, 2021). "The promising effects of this compound in treating genetic diseases such as CMT2A suggests that activating MFN1/MFN2 may be a viable therapeutic option for reducing infection in instances where a pathogen induces mitochondrial fragmentation for survival." (PMID 34337844, 2021). "Moreover, treatment of BMDMs with mdivi-1, the general inhibitor of mitochondrial fragmentation, decreased inflammatory cytokine generation, suggesting a unique role for MFN2 in the regulation of macrophage inflammatory responses during infection." (PMID 33972668, 2021). "Mtb H37Rv (Rv) infection induced mitofusin 2 (MFN2) degradation, leading to mitochondrial fission." (PMID 31671648, 2019). "The cells infected with Mfn2 shRNA showed increased lipidated and autophagosome-associated form of LC3 (LC3-II), the hallmark of autophagic processing at the molecular level, from the second day after shRNA infection, as compared with scramble controls." (PMID 25781899, 2015). "The average 1.6-fold increase of LC3-II protein level over the scramble control could be significantly diminished, though not completely blocked, by co-expression of Mfn2 cDNA with shRNA, to 82.5±3.91% of that with only Mfn2 shRNA infection." (PMID 25781899, 2015). "On day 60 after infection, developed secondary follicles and fresh corpora lutea remained visible in the ovaries, suggesting that Mfn2 may be involved in the growth and development of follicles." (PMID 25120590, 2014). "MFN2 expression in rat muscle was increased dramatically by Ad-MFN2 infection." (PMID 23815800, 2013).
infection (continued). "Interestingly, following Vpr transfection or Lenti-Vpr infection, the expression level of Mfn2 was markedly reduced, while that of GRP78 was significantly increased." (PMID 22438978, 2012). "Notably, compared with control cells, MMP loss was reduced in VprBPKD-, DDB1KD-, and CUL4AKD- cells after Lenti-Vpr infection, indicating that Vpr targeted Mfn2 to damage mitochondria through interacting with VprBP-DDB1-CUL4A ligase complex." (PMID 22438978, 2012). "However, in light of the finding that mitochondrial ER coupling orchestrated by MFN-2 inhibits mitophagy initiation, we posit that overexpression of MFN-2 will enhance ER-mitochondria tethering and prevent mitophagosome formation during EV-D68 infection, thereby reducing viral release." (PMID 39677747, 2024). "Therefore, we explored whether mtROS generation differs between Mfn2 WT and Mfn2 CKO BMDMs during infection." (PMID 33972668, 2021). "Previous studies have shown that MFN2 acts as a major regulator of the immune response by binding to NLRP3 and promoting IL-1β secretion after infection with the virus." (PMID 36968589, 2023). "During infection with human immunodeficiency type 1 (HIV-1) in macrophages, Mfn2 was up-regulated by TREM1." (PMID 35958608, 2022). "MFN2 is required for MMP homeostasis and IL-1β secretion after infection with RNA viruses, including influenza, measles, or encephalomyocarditis virus (EMCV)." (PMID 34482801, 2021). "During infection with human immunodeficiency type 1 (HIV-1), MFN1 and MFN2 are upregulated in macrophages in a TREM1-dependent manner." (PMID 34482801, 2021). "To gain further insight into the mechanism of antimicrobial defense by MFN2, we next compared mitochondrial dynamics between Mfn2 WT and Mfn2 CKO BMDMs during infection." (PMID 33972668, 2021). "We foundthat there was a significant increase of Mfn1 and Mfn2 levels in theinfected lung tissues compared to tissues without the infection bySARS-CoV-2." (PMID 38386664, 2024). "To test if the 3C protease is responsible for MFN-2 cleavage during EV-D68 infection, we incubated cell lysate (with and without MFN-2 overexpression) with EV-D68-3C-protease in vitro." (PMID 39677747, 2024). "An earlier study showed that after infection with influenza virus or encephalomyocarditis virus (EMCV), MFN2 could interact with NLRP3 to promote the recruitment of NLRP3 to mitochondria, and subsequently induce IL-1β secretion." (PMID 35250595, 2022). "Intriguingly, MFN2-mediated HIF-1α activation is augmented by mitochondrial respiratory chain complex I and ROS and contributes to macrophage-mediated inflammatory responses during infection." (PMID 34482801, 2021). "Our data are important to show that MFN2 is critically required for xenophagy activation, but not mitophagy, during infection." (PMID 33972668, 2021). "MFN2 did not impact mitophagy during infection; however, it promoted xenophagy activation through HIF-1α." (PMID 33972668, 2021). "The levels of mfn-1 and mfn-2 were significantly decreased by ~2-fold in cholesterol treated infected cells, whereas mfn-2, but not mfn-1, was downregulated by ~2-fold during infection in untreated cells." (PMID 29067283, 2017). "Given that MFN2 is involved in the regulation of aerobic glycolysis, we next questioned whether oxidative phosphorylation differed between Mfn2 WT and Mfn2 CKO macrophages after infection." (PMID 33972668, 2021). "Therefore, our work suggests that MFN2 functions in the suppression of macrophage differentiation into the M2 phenotype as well as driving aerobic glycolysis and inflammatory responses through HIF-1α during infection." (PMID 33972668, 2021). "However, it remains unclear why MFN2 but not MFN1 is required for immunometabolic remodeling in macrophages during infection." (PMID 34482801, 2021).
infection (continued). "After infection of PS2 D439A mutant SH-SY5Y cells with Ad-Miro2 adenovirus, the increased expression of Miro2 resulted in increases in the Mfn1 and Mfn2 levels but not the Drp1 level compared to those in the Ad-NC group." (PMID 38159198, 2024). "Indeed, we also observed increased growth rate and distinct cell shape of Mfn2-null MEF as compared with wild type MEF (data not shown), however, transient knockdown of Mfn2 by shRNA infection to HeLa cell or T/G HA-SMC suppressed cell growth as comparing with scramble control cells." (PMID 25781899, 2015).
metabolic disorders (13 papers, 2018 to 2025). "The recent discovery that humans homozygous for the MFN2 R707W mutation manifest striking adipose redistribution associated with serious metabolic disease is probably the clearest example to date of a causal link in humans between a mitochondrial perturbation and adipose dysregulation." (PMID 36722855, 2023). "This fission-biased phenotype, characterized by DRP1 upregulation and/or MFN2 downregulation, is a conserved feature of metabolic diseases and diabetic neuropathy." (PMID 40646155, 2025). "Similar to our results, another study found that mfn2 transcript levels were elevated in human and rat chondrocytes during metabolic disorders and inflammation." (PMID 34712228, 2021). "As recently reviewed, mitofusin 2 is involved in several cell pathways, as well as in the pathogenesis of metabolic disorders." (PMID 31835890, 2019). "Although abnormal adipose growth and metabolic disease were not seen in KI mice, the low plasma leptin concentration seen in human adipose overgrowth associated with MFN2 mutations was replicated." (PMID 36722855, 2023). "Altogether, the effects of MFN2 depletion are consistent with a greater pathophysiological relevance of MFN2 than of MFN1, exemplified by the involvement of MFN2 in metabolic disorders and neurodegeneration." (PMID 39929801, 2025).